AXIN2 (axin 2)
Diseases named in the same sentence as AXIN2 in open-access papers (continued):
Sharing a sentence is not in itself a finding about the gene and the disease.
cancer (165 papers, 2009 to 2025). A tumor composed of atypical neoplastic, often pleomorphic cells that invade other tissues. "Previous studies have shown that MEK inhibitors reduce cell proliferation but increase the expression of genes such as Ctnnb1, Axin2, and Lgr5, which are highly associated with cancer development." (PMID 38277448, 2024). "AXIN2 rs11079571, rs1133683 and rs35285779 polymorphisms have significant correlations with overall cancer risk." (PMID 33794810, 2021). "The meta-analysis results revealed that AXIN2 rs11079571, rs1133683 and rs35285779 polymorphisms were significantly associated with overall cancer risk." (PMID 34452579, 2021). "The association of genetic polymorphisms at Axis inhibition protein 2 (AXIN2) gene and susceptibility to different cancer has attracted much interest." (PMID 34452579, 2021). "Previous studies have also demonstrated the association between AXIN2 and cancer risk and susceptibility." (PMID 33794810, 2021). "In order to get an overall, accurate and updated results about AXIN2 polymorphism and cancer risk, we conducted this study." (PMID 33794810, 2021). "The AXIN2 gene is located on chromosome 17q23-q24, which belongs to a heterozygosity region that frequently loss in different cancers in human." (PMID 34452579, 2021). "An updated analysis was performed to analyze the correlation between AXIN2 polymorphisms and cancer risk." (PMID 33794810, 2021). "Other genes participating in this pathway frequently mutated in cancer include AXIN2/Axin2 (LOF) as well as CTNNB1/Ctnnb1 gain-of-function (GOF), the last encoding for the β-catenin protein." (PMID 34956074, 2021). "One study found subjects with dental agenesis had a major chance of family history of cancer and associations with AXIN2, FGF3, FGF10, and FGFR2 genes." (PMID 34378652, 2021). "Their results showed that AXIN2 rs2240308 polymorphism was correlated with decreased risk of cancer by ethnicity." (PMID 34452579, 2021). "Variation marking AXIN2 (rs2240308 and rs11867417) have been shown to be associated with cancer and orofacial phenotypes such as cleft lip and palate and tooth agenesis." (PMID 32184411, 2020). "Tooth loss/edentulism was associated with two AXIN2 SNPs in the cancer-affected sample, increasing up to 2.3 times the chances of losing teeth." (PMID 32184411, 2020). "An updated analysis was conducted to ascertain a more accurate estimation of the correlation between AXIN2 148 C/T, 1365 C/T, and rs4791171 A/G polymorphisms and cancer risk." (PMID 31080360, 2019). "We also used in silico tools to assess the effect of AXIN2 expression on cancer susceptibility and overall survival time." (PMID 31080360, 2019). "Many epidemiological studies have investigated association of AXIN2 variants on overall cancer risks; however, the available results remain inconsistent." (PMID 31080360, 2019). "Firstly, a comprehensive study of the correlation of the AXIN2 148 C/T, 1365 C/T, and rs4791171 A/G variants with overall cancer susceptibility is statistically more powerful than single case–control study." (PMID 31080360, 2019). "Axin2 is involved in the regulation of Wnt/β-catenin pathway and implicated in cancer development and progression." (PMID 25974148, 2015). "The pooled odds ratios (OR) and the 95% confidence intervals (CIs) were assessed to evaluate the association of the AXIN2 rs2240308 polymorphism with a susceptibility to cancer." (PMID 25974148, 2015). "It has also been reported that AXIN2 mutations lead to increased β-catenin concentrations in cancer with defective mismatch repair systems." (PMID 26161041, 2015). "The ORs and their respective 95% CIs were used to evaluate the association between AXIN2 rs2240308 and cancer risk." (PMID 25974148, 2015). "The association between AXIN2 rs2240308 polymorphism and cancer risk has been examined in several case-control studies, but the conclusions were conflicting." (PMID 25974148, 2015).
cancer (continued). "The objective of this study is to evaluate broadly the evidence available for the AXIN2 rs2240308 polymorphism and risk of cancer." (PMID 26161041, 2015). "The objective of this meta-analysis is to evaluate broadly the available evidence on the AXIN2 rs2240308 polymorphism and risk of cancer, for deriving a more reliable assessment." (PMID 26161041, 2015). "Because the AXIN2 mutation (c.314T>G) identified in the present study occurred de novo, cancer prevention measures are necessary for the 8-year-old male proband." (PMID 26406231, 2015). "To investigate the association between the AXIN2 rs2240308 polymorphism and risk of cancer in different cancers, we also performed a subgroup analysis by cancer type." (PMID 26161041, 2015). "In the random-effects model, the AXIN2 rs2240308 G allele increased the overall risk of cancer significantly compared with the A allele." (PMID 26161041, 2015). "This is the first meta-analysis of the association between the AXIN2 rs2240308 polymorphism and risk of cancer." (PMID 26161041, 2015). "Some studies focused on the associations between risk of cancer and single nucleotide polymorphisms (SNPs) of the AXIN2 gene, such as rs3923086, rs3923087, and rs2240308." (PMID 26161041, 2015). "The mutation of the Axin2 gene and the loss of heterozygosity in the genomic locus have been observed in certain cancers, including colorectal, hepatocellular and ovarian cancer." (PMID 25013500, 2014). "Compared to the homozygous genotype ‘AA’ in the AXIN2 rs3923087, the heterozygotes ‘AG’ showed about 2.7 fold decrease risk of developing cancer (OR, 0.373; CI, 0.193–0.720; p = 0.00298)." (PMID 23516639, 2013). "Thus, we designed this meta-analysis to obtain updated and accurate insight to assess the association between AXIN2 polymorphism and cancer susceptibility." (PMID 33794810, 2021). "So, we preformed this meta-analysis to the current evidence for AXIN2 polymorphism to cancer risk." (PMID 33794810, 2021). "As the expression or protein structure may be influenced by gene polymorphism, some studies have taken insights in the correlation between AXIN2 and cancer susceptibility." (PMID 33794810, 2021). "In conclusion, our updated study suggests that AXIN2 rs11079571, rs1133683 and rs35285779 polymorphisms are associated with overall cancer susceptibility, which may provide a new insight to understand the correlation between AXIN2 gene and cancer risk." (PMID 33794810, 2021). "This family was identified through a Mayo Clinic pilot program testing patients newly diagnosed with all types of cancer for germline variants in 83 cancer- related genes, including AXIN2 (INTERCEPT study)." (PMID 32807118, 2020). "The genetic connection between alterations in embryonic development of dental organs and predisposition to cancer is understandable; particularly the finding that AXIN2 mutations could lead to an inefficient block of the WNT signaling pathway." (PMID 31632692, 2019). "Therefore, a meta analysis with all eligible data based on the inclusion criteria was conducted to further assess the associations between AXIN2 148 C/T, 1365 C/T, and rs4791171 A/G polymorphisms and cancer risk." (PMID 31080360, 2019). "Our findings indicated that AXIN2 148 C/T and 1365 C/T variants may be associated with decreased cancer susceptibility." (PMID 31080360, 2019). "Notably, we observed that methylation of DKK1 is high in BRAF mutant and CIMP (CpG island methylator phenotype)-positive cancers, whereas AXIN2 methylation appears to be associated with CMS4." (PMID 28368388, 2017). "Therefore, the overall assessment of the association between AXIN2 polymorphisms and cancer would be moderate cumulative evidence (Venice criteria grades = BBA)." (PMID 26161041, 2015). "Variants in the axis inhibition 2 (AXIN2) gene might alter the protein’s structure or function or create a multiprotein destruction complex in the Wnt signaling pathway and thus affect an individual’s susceptibility to cancer." (PMID 26161041, 2015).
cancer (continued). "Moreover, ChIP-chip assays yielded a total of 48 genes enriched in at least three of the seven primary samples including genes associated with cell cycle such as ARGHEF2, CCNA2, CDKN2D, GAK2, ORCL6, PCPNP, and TACC1 and genes associated with cancer such as AR, AXIN2, IKBKG, ETS1, PTPN11, and WNT2B." (PMID 23300998, 2013). "Expression levels of cancer stem cell (CSC) marker genes Lgr5, Smoc2, Axin2, Rnf43, and CD44 were markedly reduced in Prrc2a‐deficient tumors induced by AOM‐DSS treatment." (PMID 39582289, 2025). "CYMP-AS1 exerted pro-cancer effects by binding to hnRNPM, reducing the mRNA stability of AXIN2, and modulating the Wnt/β-catenin signaling pathway, ultimately accelerating the OC progression." (PMID 40746892, 2025). "This expands the known functions of the miR-1275/AXIN2 axis beyond its established roles in cancer and highlights its potential therapeutic implications in degenerative disorders such as IDD." (PMID 40476182, 2025). "Stabilization of AXIN1 and AXIN2 by inhibiting their degradation through tankyrase (TNKS) allows the attenuation of Wnt signaling in cancer, attracting interest for potential targeted therapy." (PMID 39022865, 2025). "This was accompanied by a decrease in gene expression of cancer related genes (Myc, Axin2, Gimap1/6/8)." (PMID 39523394, 2025). "The remaining 45 cancers carry additional truncating mutations in either AXIN1, AXIN2 or AMER1, or defective missense or truncating RNF43 mutations." (PMID 39674817, 2025). "Alterations in both Axin1 and Axin2 have been observed in various human cancers and cancer cell lines." (PMID 38534454, 2024). "AXIN2 is a scaffolding protein of the Wnt signaling pathway and promotes cancer-cell invasion and metastasis in various types of cancers." (PMID 37830558, 2023). "We found higher levels of epithelial stem cell/cancer stem cell markers (e.g., Lgr5, Axin2, Cd44, Prom1/CD133) in the tumoroids derived from ApcMin/+ WT as compared with ApcMin/+ Stat2−/− mice." (PMID 38001683, 2023). "The importance of the Wnt-signalling pathway and its antagonist’s sFRP, DKKs and Axin2 for cancer is outlined in the introduction." (PMID 35101137, 2022). "Five genes, AXIN2, BMP1, CR1, ERBB2, and RYR1, have been recorded of association with birth defects and cancer." (PMID 36384586, 2022). "Among genes participating in this signaling pathway, AXIN2 and TCF7L2 have shown an association with different cancers." (PMID 35996498, 2022). "Several studies have investigated the association of the AXIN2 and TCF7L2 polymorphisms with cancer." (PMID 35996498, 2022). "TFRC (transferrin receptor) promoted the proliferation and metastasis of cancer cells by upregulating the expression of AXIN2, which accelerated the development of cancer." (PMID 35807355, 2022). "BC2059 has been shown to inhibit β-catenin activation of several cancer genes, such as AXIN2 and BIRC5, with minimal effects on the maintenance of normal tissue functions." (PMID 36240209, 2022). "The regulatory axis of canonical Wnt-dependent Axin2 plays an important role in the regulation of Snail (SNAI1) mediated EMT in cancer, is a typical downstream target of the TCF/LEF transcript factor, and is highly abundant in CRC due to the loss of APC." (PMID 34298652, 2021). "TI-12403 induced AXIN2 expression and downregulated β-catenin, increasing the sensitivity of cancer cells." (PMID 34298950, 2021). "In various types of human cancer and precancer tissue, Axin and Snail protein are consistently co-localized, which supports that Axin2 serves as an oncogenic role by inducing Snail-mediated EMT." (PMID 34572856, 2021). "The canonical Wnt pathway directly regulates cancer EMT programs via activation of the β-catenin/TCF complex-regulated Axin2/GSK3β/Snail cascade." (PMID 34572856, 2021). "Stabilization of AXIN2 protein in cancer cell lines inhibited Wnt signaling, migration, and under low serum conditions, reduced colony formation." (PMID 34452579, 2021).
cancer (continued). "As the results showed in Figures and Tables, we concluded that AXIN2 rs11079571 had significant correlation with overall cancers and Asian population subtype." (PMID 33794810, 2021). "Axis inhibition protein 2 (AXIN2) was reported as an oncogene and participates in the regulation of cell proliferation, migration, and other functions in several human cancers." (PMID 33824474, 2021). "We found that AXIN2 staining was medium in normal tissues but low in cancer tissues, and the number of normal tissues was higher than that of cancer tissues." (PMID 33401247, 2020). "Consistent with previous observations in other cancers, our results imply that the Axin2-Snail axis is a poor prognostic indicator of OSCC." (PMID 33046030, 2020). "Another component of the destruction complex, Axin, also functions as a negative regulator of cancer growth, and two isoforms (Axin1 and Axin2) function equally in the Wnt signaling pathway." (PMID 32486158, 2020). "We had examined the expression of β-catenin, Snail, or Axin2 according to the CK2 activity of cancer cells." (PMID 29540671, 2018). "Less frequently, loss-of-function mutation of AXIN1, AXIN2, or APC is found in 3.2%, 0.4%, and 0.2% of HCCs respectively, evidently contrasting with the situation in colorectal cancer, where up to 80% of cancers display mutated APC." (PMID 28035485, 2017). "Its growth inhibitory properties were observed mainly in β-catenin-activated embryonic cells and cancer cells, and were associated with decreased expression of c-MYC, cyclin D and AXIN2." (PMID 24595456, 2014). "The Wnt signaling pathway plays a crucial role in human cancer development, and axis inhibition protein 2 (Axin2) is a master scaffold protein involved in Wnt signaling." (PMID 25013500, 2014). "Axin2 crucially participates in cancer development through modulating the signaling pathway." (PMID 40746892, 2025). "Specifically, cancers with SALL2 mutations displayed upregulated WNT7B and downregulated AXIN2." (PMID 40869218, 2025). "Multiple studies indicate that the canonical Wnt signaling pathway and the AXIN2 gene, which acts as a critical negative regulator to preserve the stability of β-catenin, are significant factors in cell growth, cancer development, tumor progression, and tooth formation." (PMID 38523193, 2024). "Finally, we validated that miR-1275 regulates cancer cell killing ability by NK-92 cells through regulating AXIN2 expression." (PMID 38035113, 2023). "And AXIN2 upregulation could significantly reverse the promotion of miR-1275 overexpression on NK-92 cancer cell killing." (PMID 38035113, 2023). "Consistent with our previous results, the results of functional experiments also showed that AXIN2 overexpression was able to significantly attenuate the restorative effect of upregulated miR-1275 upon the killing ability of NK cells against cancer cells under hypoxic environments." (PMID 38035113, 2023). "Examination of DES cluster 5 for expression of Wnt signaling targets, however, indicated that relative to other DES clusters, the DES cancer cells had among the lowest expression of Wnt ligands, receptors, and target genes including Wnt7a, Ccnd2, Axin2, and Myc." (PMID 37856394, 2023). "Taken together, these results suggest that the role of AXIN2 may be different for each cancer, and BRAF mutations may affect AXIN2 expression." (PMID 35550582, 2022). "Numerous studies have reported the correlation between AXIN2 polymorphism and cancer risk, but the results seem not consistent." (PMID 33794810, 2021). "In recent years, many studies have pointed out that genomic types may be closely related to the carcinogenic effects of cancers, one of which is the Axin-related protein, AXIN2." (PMID 33794810, 2021). "Judge from the studies related to AXIN2 polymorphism and cancer risk and susceptibility, the results seem not consistent." (PMID 33794810, 2021).
cancer (continued). "Other studies have similarly found a link between Axin2 mutations and cancers, but to date, no large studies have been conducted." (PMID 34858573, 2021). "Axin2-mediated Snail stabilization may contribute to cancer-stromal crosstalk and thereby may influence cancer prognosis." (PMID 33046030, 2020). "Oncogenic activities of the Axin2-Snail axis are not limited to the cancer cells themselves but rather extend to CAFs via regulation of the cytokine-mediated cancer-stromal interaction, with further implications for bone invasion as well as a poor prognosis in OSCC." (PMID 33046030, 2020). "Alternations of Axin1 and Axin2 have been detected in diverse human cancers and cancer cell lines." (PMID 32486158, 2020). "The hyperexpression of WNT target genes corresponds with the hyperactivated WNT pathway in primary CRC and CRC cancer cell lines, most likely resulting from the biallelic inactivation mutation of APC, FBXW7, AXIN2, and FAM123B or the activating mutations in CTNNB1." (PMID 30363662, 2018). "In agreement, our real-time PCR analysis demonstrated that the mRNA level of oncogenic genes including cMyc, cyclin D1 and cancer stem cell associated markers, CD44, β-catenin and Axin-2 was all up-regulated in the spheres as compared to their parental counterparts." (PMID 30005681, 2018). "In a recent study, we suggest that polymorphic variants in AXIN2 and CDH1 may be associated with NSCL/P susceptibility, and reinforce the putative link between cancer and oral clefts." (PMID 29274157, 2018). "The results suggest that polymorphic variants in AXIN2 and CDH1 may be associated with NSCL ± P susceptibility, and reinforce the putative link between cancer and oral clefts." (PMID 28376813, 2017). "Interestingly, recent studies have demonstrated a relationship between congenital malformations and malignancies, and genetic alterations in AXIN2 and CDH1 are associated with both NSCL ± P and cancer of breast and gastric." (PMID 28376813, 2017). "Alterations in the Axin2 gene have been detected in several cancer types." (PMID 25013500, 2014). "This association indicates the possibility that the variations in the Axin2 gene in this position may play a significant role in promoting the development of cancer in the prostate." (PMID 25013500, 2014). "In addition, we identified an apparent increase in methylation alterations of AXIN2 from SSAs to MSI carcinomas, suggesting that its expression deregulation by methylation associates with the serrated adenoma-MSI cancer pathway." (PMID 24964857, 2014). "In addition, CGK062 repressed the expression of the genes encoding cyclin D1, c-myc, and axin-2, β-catenin target genes, and thus inhibited the growth of CRT-positive cancer cells." (PMID 23071615, 2012). "The logistic regression models evaluating associations between the genetic variants—WNT11 (rs1533767) and AXIN2 (rs3923087 and rs11867417)—and OPMD/OSCC confirmed the allelic associations, suggesting that family history of cancer and smoking habits may act as confounding variables." (PMID 40960755, 2025). "The mutation of AXIN2 or APC gene may change the conformation of the binding site of the 2 proteins, resulting in a decreased affinity between the 2 proteins and the occurrence of cancer." (PMID 36042639, 2022). "Although it is not yet known how the rs2240308 SNP is associated with cancer, one mechanism may be explained by the alteration of the coding amino acid at the affected position of the Axin2 protein." (PMID 25013500, 2014). "Stromal fibroblasts from both normal and cancer donors promoted the upregulation of stemness-related genes (ALDH1, AXIN2, CD133, MYC, and SOX9) in EEC organoids." (PMID 39229264, 2024). "AXIN2 expression is driven by MYC and overexpressed in multiple human cancers critical to maintain cancer cell aggressiveness via regulation of the beta catenin/wnt pathway." (PMID 36130950, 2022).